RELA (RELA proto-oncogene, NF-kB subunit)
Diseases named in the same sentence as RELA in open-access papers (continued):
Sharing a sentence is not in itself a finding about the gene and the disease.
tumor (continued). "Moreover, DGKα is involved in inflammation in tumor cells by positively regulating tumor necrosis factor α (TNFα)-induced nuclear factor kappa-light-chain-enhancer of activated B cells (NF-κB) activation via a PKCζ-mediated Ser311 phosphorylation of the NF-κB subunit p65/RelA." (PMID 32722576, 2020). "NFкB (RelA) is documented to be highly active in GBM and known to upregulate inflammatory microenvironment and tumor aggressiveness in GBM." (PMID 31992226, 2020). "The tumor suppressive functions of canonical NF-κB may also be attributed to an attenuated inflammatory response.NF-κB p50 subunit functions as a transcriptional regulator either as a heterodimer with NF-κB subunits RelA, c-Rel, and RelB, or as a p50 homodimer." (PMID 29601548, 2018). "As expected, we found the activation of the TNF‐α/NF‐κB axis, and the knockdown of TNFR1, RelA, RelB, c‐Rel, and CUL4B showed similar effects on the proliferation, invasion, colony formation, and the in vivo tumor forming ability of cells." (PMID 29377600, 2018). "Collectively, these results suggest PKCε-mediated MIIP-S303 phosphorylation facilitates the interaction between MIIP and RelA, which is required for EGF-induced tumor cell invasion." (PMID 29038521, 2017). "Within this network, several genes were identified namely CCND1, RELA, TP63, and EGFR as being major contributors to tumour cell proliferation, immortalization, and metastasis in oral tumourigenesis." (PMID 28384287, 2017). "Similar with that of HCT116, MIIP S303A expression which blocked promoter-enrichment of MIIP or RelA Ac-K310 in CaCo2 cells, inhibited transcription of MMP2 and Twist and tumor cell invasion." (PMID 29038521, 2017). "Intriguingly, phosphorylated MIIP protects deacetylation of RelA from HDAC6, thereby ensures EGFR-stimulated RelA transcriptional activity and potentiates tumor metastasis." (PMID 29038521, 2017). "Further analysis of these tumours revealed overall lower levels of apoptosis, but increased levels of proliferation in DEN-treated livers from RelA T505A mice." (PMID 26853469, 2016). "Further, LZAP inhibits cellular transformation, xenograft tumor growth, and xenograft tumor vascularity at least partially through LZAP's ability to bind and inhibit RelA." (PMID 21283629, 2011). "Based on shRNA screening for the upregulated genes in in vitro carboplatin-resistant cells, we found that simultaneous knockdown of RELA and STAT5B was most effective in sensitizing tumor cells for carboplatin treatment." (PMID 20585448, 2010). "Cytoplasmic RelA overexpression was observed in high-grade pancreatic intraepithelial neoplasia (PanIN III), in the vicinity of invasive tumour." (PMID 17622249, 2007). "Furthermore, Maelstrom (MAEL) increases phosphorylated Akt1 expression in tumor cells, which phosphorylates the NF-κB subunit RelA, resulting in MDSC chemotaxis through the upregulation of CXCL8, thereby accelerating tumor progression within the TME." (PMID 40134607, 2025). "Studies have demonstrated that METTL3 enhances tumor cell proliferation and invasion through the MYC, inhibitor of nuclear factor kappa-B kinase subunit beta (IKBKB), and RELA proto-oncogene, NF-kB subunit (RELA) signaling pathways." (PMID 40678060, 2025). "We performed transcription factor (TF) enrichment analysis on the identified key genes and found that TFs such as HAND1, RELA, and CLOCK were upregulated in the tumor margin, whereas members of the zinc finger family were predominantly upregulated in the tumor center." (PMID 40741331, 2025).
tumor (continued). "Here we report that in contrast to the tumor-promoting role of RelA, NF-κB2 intrinsic to lung epithelial and tumor cells had no marked effect on lung tumorigenesis and progression." (PMID 38385745, 2024). "These RelA-MUT GSC11 lines failed to initiate tumor growth in vivo, highlighting its reliance on NF-κB signaling." (PMID 37461511, 2023). "Significantly, in the early stages of tumour development, both NFKB1/RELA and PIEZO1 displayed heightened expression levels, paralleled by similar kinetic trends of proliferation‐associated genes such as CDK6, CCND1 and CCND3, as unveiled by functional pseudotime analysis of the scRNA‐seq dataset." (PMID 37983931, 2023). "Analysis for the differential RELA gene expression in HNSCC samples from the UALCAN database showed statistically significant difference only between tumor stages I and IV, but no positive correlation between male and female patients." (PMID 36766673, 2023). "The entire locus is embedded in a cluster of 27 cCREs, and all replicates show a broad RNAPII signal in normal tissue but not RELA-driven tumor encompassing the entire cluster." (PMID 37739938, 2023). "Additionally, we found experimentally that miR-335-5p displayed tumor-suppressive properties in EOC cell lines, was regulated by both RELA and RELB, and, by mimicking its expression, suppressed TIC viability." (PMID 37175530, 2023). "Moreover, a decrease in the levels of RELA, NOD1, CASP8, BCL2L1, ELK1, and IKBKB was identified in poorly differentiated tumours compared to moderately differentiated tumours." (PMID 36433652, 2022). "In GC, NFKB1, NFKB2, REL, RELA, and RELB were significantly upregulated in tumor tissues." (PMID 35036435, 2022). "Clustering analysis revealed nine RELA+, one YAP1+, and six unclassified tumours." (PMID 34314101, 2021). "The TF–target gene network analysis uncovered an unexpected scenario where both correlation-enhancing genes (with higher correlation in the tumor) and -repressing genes (with lower correlation in the tumor) were targeted by STAT1 (6A), STAT3 (6B), KDM1A (6C), PML and RELA." (PMID 33384992, 2020). "Thus, when RELA and STAT1 were up-regulated in a tumor, parallel to doxycycline added in vitro, the genetic circuit was then switched on." (PMID 32712598, 2020). "Interestingly, most deregulated genes, such as IL6, RelB, RelA, Plac8, ITGA5, CXCL12 and FN1, among other cytokines and growth factors, have been involved in tumor growth and progression." (PMID 32848147, 2020). "Next to RELA, the NF-κB subunit c-REL was likewise shown to possess a key role in tumor formation." (PMID 29673141, 2018). "There was no preferred age of onset, intracerebral location or tumor form (cystic or solid) in C11orf95-RELA-positive EPNs, as compared to RELA-negative tumors." (PMID 30514397, 2018). "Moreover, we show that genetic and chemical downregulation of HGFL-RON signaling disrupts BCSC phenotypes and tumor growth by suppressing the RON-mediated phosphorylation/activation of β-CATENIN/CTNNB1 and its effector NF-κB/RELA." (PMID 28938607, 2017). "NF-κB subunit expression was also examined in respect to tumor grade, revealing no changes in RelA and P100/P52 expression, but enhanced P50 and RelB expression with increasing tumor grade." (PMID 29371965, 2017). "By contrast, although NF-κB-dependent control of JNK activity in the liver has been linked to regulation of its target gene Gadd45β,17 we did not observe any changes in its expression in RelA T505A tumours." (PMID 26853469, 2016).
tumor (continued). "The results showed significantly enhanced expression of RelB, but not RelA, in EC tumor cell specimens." (PMID 27711077, 2016). "Patients with cytoplasmic negativity for RelA in the tumour survived for a median time of 16.3 month as opposed to a median survival time of 13.3 month in the group of patients whose tumours showed high RelA expression in the cytoplasm (P=0.034)." (PMID 17622249, 2007). "Moreover, the survival and the migratory capability of RelA-depleted cells were also greatly recovered by ALDH1B1 overexpression, whereas RelA depletion showed no significant impact on lipid peroxidation or survival in unconfined tumor cells." (PMID 41390768, 2025). "Finally, to evaluate whether IDR3 was necessary and sufficient to initiate tumours when fused to ZFTA, we created a minimal construct that expressed ZFTA-N fragment joined to IDR3, eliminating most of IDR2 and the RHD region of RELA." (PMID 40866513, 2025). "Surprisingly, RelA mutant GSC11 failed to initiate tumor growth in vivo (data not shown)." (PMID 37461511, 2023). "Therefore, in contrast to NEMO that appears to be essential for SCLC, RelA promotes tumor initiation and growth but is not necessary for SCLC development." (PMID 36653597, 2023). "CBD can mediate the cytotoxicity of human primary GBM stem-like cells (hGSCs) by promoting the DNA binding of NF-κB subunit RELA and simultaneously prevent RELA phosphorylation, suggesting that NF-κB can be converted into a tumor suppressor via non-psychotropic CBD." (PMID 38068944, 2023). "Furthermore, NGS analysis revealed that NF-κB/RELA targets including CCL2, CXCL8, EDN1, IL-1β, IL-6, and SERPINE1 were further reduced and several potential tumor suppressors, such as FABP3, FADS2, FDFT1, SEMA6A, and PCK2, were synergistically induced by the Gefitinib-+IKK16 treatment." (PMID 36358633, 2022). "However, in our model, loss of downstream IL-1 signaling mediators, such as MYD88 and RELA, did not affect the tumor-promoting function of the enteric glia." (PMID 33282743, 2020). "Since FAT1 and NFкB (RelA) are independently known to promote pro-tumorigenic inflammation and upregulate the expression of HIF-1α/EMT/stemness in tumors, targeting the NFкB (RelA)-FAT1 axis may attenuate an important tumor-promoting pathway in GBM." (PMID 31992226, 2020). "Functional blockade of NFKB in epidermal cells resulted in severe hyperplasia of the skin in the transgenic mice, and effect that could be reversed by the overexpression of active RELA and the NFKB1 subunit of NFKB, suggesting that NFKB has a tumor suppressive effect." (PMID 31363162, 2019). "To evaluate whether knocking down RelA, RelB, and c‐Rel results in similar suppressive effects in vivo, we injected nude mice with RelA, RelB, c‐Rel, or control shRNA‐transduced U2OS cells and monitored the tumorigenesis for 30 days by measuring tumor volumes at 5‐day intervals." (PMID 29377600, 2018). "In accordance, immunoblotting analysis of mice tumor tissues indicated WT rMIIP but not rMIIP S303A underwent S303 phosphorylation during tumor growth, and RelA Ac-K310 levels was attenuated in tumor tissues from cells with rMIIP S303A expression in a HDAC6 dependent manner." (PMID 29038521, 2017). "Previous report also shows O2-• bust to damage cancer cells under high fluence LPLI, which suggest that H2O2 may trigger RelA/BECN1-mediated autophagy as a survival mechanism, whereas O2-• confers to tumor suppressive effects in cancer cells under LPLI exposure." (PMID 27632526, 2016). "In addition to the classical activation of RelA/NF-κB, more attention should be paid to the noncanonical RelB/NF-κB pathway in specific tumor types." (PMID 27711077, 2016). "The RelA to IRF signaling pathway may also originate a robust tumor-suppressor pathway, which may be defeated in many progressively growing cancers and possibly contributing to escape from tumor immune surveillance." (PMID 26460486, 2015).
tumor (continued). "The direct effect of CXCL12/CXCR4 in tumor metastasis is that CXCL12 increases CXCR4-mediated motility, and the cell surface expression of integrins is mediated by the phosphorylation of extracellular signal regulated kinase (ERK) and downstream activation of the IKKαβ/NFκβ/RELA signaling." (PMID 24944647, 2014). "With IVA, there was four bone-related processes brought front only in the case of the tumour tissue—“myelopoiesis of bone marrow” (NPM1, RARA), “quantity of trabecular bone” (CREBBP, SMO), “outgrowth of bone marrow cells” (ALK) and “inflammatory response of bone marrow-derived macrophages” (RELA)." (PMID 25496518, 2014). "Moreover, while the RelA (p65) subunit of NF-κB family was shown to directly regulate YY1 expression, it was not clear if these two molecules exhibit cross talk in the regulation of gene expression and tumor survival." (PMID 23874387, 2013). "Moreover, PL2L proteins are always co-expressed with NF-κB/RelA in the cytoplasm or nucleus, suggesting that PL2L60, in cooperation with NF-κB, may play important but opposite roles to Piwil2 in tumor development." (PMID 20975993, 2010). "Furthermore, whether PDLIM2 is involved in therapeutic resistance and whether PDLIM2 exerts its tumor suppressor role through targeting RelA and/or STAT3 have not been examined in any cancer type." (PMID 31757943, 2019). "Furthermore, transwell analysis showed rMIIP S303A expression significantly inhibited EGF-induced tumor cell invasion, and no additional effects on impaired invasive ability were observed when rMIIP S303A mutant co-expressed with RelA K310R in HCT116 cells compared with its WT counterpart." (PMID 29038521, 2017). "Although the differences between RELA and PFA tumors were not significant, this finding suggested that the reduction of mCpA can be a potentially epigenetic signature of EPN tumor of which the functional roles warrant further examination." (PMID 36335125, 2022). "RelB but not RelA, was significantly upregulated in EEC, and silencing RelB in EEC cell lines affected colony formation, tumor growth in vivo and cell cycle progression." (PMID 31443240, 2019). "However, expressions of NF-κB (RelA) and JNK/pJNK reduced in response to ART in both TLR4-expressed and silenced tumor-bearing mice, indicating that TLR4 was not involved in the anti-cancer effects of ART." (PMID 38144525, 2023). "Both data suggest that, in contrast to the discovery in tumor cell entities and blood cells, TERT:RelA might not establish a reciprocal interplay in the aging CNS." (PMID 30472697, 2018). "We demonstrate that the massive production of tumor-promoting secreted factors in BrdUsen cells is, at least partly, due to the activation of the NFκB-pathway probably involving NFKB1/p50 homodimers, but not RelA/p65 as e.g. in ras-induced senescent fibroblasts." (PMID 26657295, 2016). "Moreover, the expression levels were unaffected by PDT or RelA knockdown, altogether indicating that IL-10 and IL-12 did not modulate IL-6 and TNF-α signaling and did not play a role in the PDT response by tumor cells or the immunogenicity of PDT-afflicted EMT-6 cells in macrophages." (PMID 26307977, 2015).
cancer (271 papers, 2001 to 2026). A tumor composed of atypical neoplastic, often pleomorphic cells that invade other tissues. "This leads to enhanced NF-κB/RELA complex formation, promoting transcription of pro-inflammatory genes associated with cancer progression, immune cell regulation, and macrophage polarization toward the M1 subtype." (PMID 39941858, 2025). "RELA, also named p65, is a key transcription factor of NF‐κB signaling and is implicated in the development and progression of various cancers." (PMID 40919676, 2025). "Among the top ten downregulated DEGs, the RelA gene, which encodes the NF-κB p65 subunit known to regulate cancer progression, attracted particular attention." (PMID 40860198, 2025). "Dysregulated NF-κB signaling is implicated in numerous pathologies, including cancer progression, with acetylation of RelA at lysine 310 (K310ac) being critical for its transcriptional activity." (PMID 39713312, 2024). "RelA has also been shown to modulate immune responses, and its activation is positively associated with multiple types of cancer." (PMID 39058137, 2024). "The identification of CHK1 as a putative RelA T505 kinase linked these atypical consequences of NF-κB activity to DNA replication stress, a common feature of cancer cells and to activation of oncogenes such as MYC in particular." (PMID 36240065, 2022). "We have also shown that mutation of T505 RelA to alanine results in the earlier onset of cancer, alongside an enhanced invasive phenotype, and resistance to CHK1 inhibitors." (PMID 36240066, 2022). "Consistent with this notion, siRelA/MPEG-PCL-CH2R4H2C micelleplexes successfully delivered siRNA into cancer cells in a lung metastasis mouse model, causing inhibition of RelA accompanied by significant suppression of metastasis." (PMID 34445799, 2021). "Some studies have revealed an association between elevated RELA expression and poor survival in cancer." (PMID 34321012, 2021). "Nuclear factor-κB (NF-κB) p65 encoded by RELA is involved in proliferation, progression, angiogenesis and metastasis in cancer." (PMID 34445479, 2021). "Of these TFs, as a subunit of NF-κB complex, the phosphorylation of RELA was associated with disease progression, inflammatory regulation and various cancers through NF-κB signaling pathway." (PMID 33005178, 2020). "The interplay between autophagy and EMT have been reported in other disease contexts, with a recent study demonstrating inhibition of autophagy induces EMT via p62/SQSMT1-NFκB/RELA pathway in RAS-mutated cancer cells." (PMID 31391462, 2019). "As p300 HAT is closely associated with RelA/p65 acetylation in cancer progression, several dietary compounds, such as anacardic acid, garcinol, curcumin, gallic acid, and EGCG, are reported to inhibit p300." (PMID 31248140, 2019). "Studies show that PPARδ acts as a transcriptional repressor via direct RelA (p65) binding, leading to suppression of cytotoxic T lymphocyte functions, which may cause acceleration of cancer progression." (PMID 41373990, 2025). "One main function of PDLIM2 is to promote the ubiquitination and proteasomal degradation of nuclear activated NF-κB RelA, a physiologically indispensable transcription factor whose persistent activation has been linked to almost all cancer types and inflammation-associated diseases." (PMID 39080804, 2024). "To directly identify the association of NFκB1 and RelA on MDR gene of cancer cells, we have treated EP and LP cancer cells with MDSC supernatant for a period 240 mins, keeping cancer cells without Dox as a control and then carried out ChIP assay followed by immune-precipitation." (PMID 38304256, 2023). "Similarly, except for RELA, the other encoding genes were expressed differently in the most individual cancer stages." (PMID 35787690, 2022). "Furthermore, mutations in the RelA gene have been reported in many cancers, but there have been few reports of systemic diseases due to mutations in RelA." (PMID 35887342, 2022).